ALDH1A3 (aldehyde dehydrogenase 1 family member A3)
Diseases named in the same sentence as ALDH1A3 in open-access papers (continued):
Sharing a sentence is not in itself a finding about the gene and the disease.
tumor (continued). "Considering that differentiated tumor cells constitute the major population in GB tissues, the ability of ALDH1A3 to boost proliferation in differentiated progenies of GSCs further underscores the potential merit of ALDH1A3 inhibition as a therapeutic approach." (PMID 39513909, 2024). "ALDH1A3 O/E significantly promoted tumor growth in vivo compared with that in mock cells." (PMID 38669046, 2024). "The tumor-initiating cell frequency we observe in MDA-MB-468 tumors (left) reflects CD24−CD44+ cell percentages (left) and tumor growth (left) data, and provides a probable explanation for why MDA-MB-468 cells, ALDH1A3 knockdown results in increased tumor growth." (PMID 39251846, 2024). "However, so far, little is known about the functional role of ALDH1A3 in tumor angiogenesis beyond its role as a stem cell marker." (PMID 37686698, 2023). "This expression manner found in GBM tumor tissues raised our interest to further explore whether ALDH1A3-expressing GBM tumor cells activated endothelial angiogenesis and, if so, what the underlying mechanisms were involved." (PMID 37686698, 2023). "The homeostatic level of intracellular ATP ranges from 0.5 to 5 mM22 and may change in tumor cells and upon chemotherapeutic treatment, meaning that ALDH1A3 activity could be physiologically modulated by changes in the energy status of the cell." (PMID 35418200, 2022). "After knockdown of USP22, ALDH1A3 was significantly downregulated in tumor cells." (PMID 35935969, 2022). "However, the differences in metabolite abundances was magnified in vivo, as the tumor xenografts had a significantly different metabolite profile upon ALDH1A3 overexpression." (PMID 34989902, 2022). "Moreover, it has been shown that the number of ALDH1a3-expressing cells dramatically increases in recurrent tumor growth, eventually resulting in the high therapy resistance of recurrences." (PMID 36552781, 2022). "Nevertheless, we also cannot exclude the possibility that other factors directly or indirectly related to tumor development may have elevated the baseline level of Nqo-1 and Aldh1a3 in BMDMs." (PMID 34711804, 2021). "In this study, we identified that ALDH1A3 could interact with PKM2 to modulate tumor aerobic glycolysis regulated by its upstream miR-16-5p and 15b-5p upon CuET treatment in CRC." (PMID 33419984, 2021). "Furthermore, we examined the anti-tumor effect on the vector and ALDH1A3-overexpressing KKU-M055 cells; the overexpression of ALDH1A3 in KKU-M055 cells increased the gemcitabine resistance." (PMID 34440089, 2021). "To this end, we examined whether the methylation of Nqo-1 and Aldh1a3 in BMDMs can be induced by a tumor-conditioned medium (TCM)." (PMID 34711804, 2021). "In addition, we confirmed that the expression levels of CD44 and ALDH1A3, markers of CSCs, in tumor organoids were significantly lowered after KYA1797K treatment." (PMID 32457491, 2020). "Indeed, FACS analyses revealed that MMTV‐PyMT;TgfbiΔ/Δ tumours have reduced numbers of ALDHhigh cells and express lower levels of Aldh1a3." (PMID 33080107, 2020). "ALDH1A3 positive cells were mostly located at the tumor infiltrative area, suggesting that ALDH1A3 may participate in tumor cell invasiveness and metastasis." (PMID 32680476, 2020). "Finally, we also observed the expression of ALDH1A3 frequently in the outer layer of different stage of glomeruloid tufts and in some endothelial cells of tumor vessels." (PMID 32680476, 2020). "Additionally, chi-square test indicated the higher proportion of ALDH1A3-positive expression cases in patients with tumor size larger than 4 cm (p = 0.046) and in patients with distant metastasis (p = 0.028) in PDAC patients." (PMID 32612951, 2020). "In addition, levels of the luminal progenitor marker Aldh1a3 was exclusively detected in PyMT tumor cells, indicating that these tumors consist of cells associated with a primitive luminal cell state." (PMID 32840210, 2020).
tumor (continued). "Similarly, ALDH1A3 expression was also found to be significantly increased in patients with worse outcome, playing a key role in tumor progression." (PMID 31191243, 2019). "MUC4 knockdown in MDA-MB-231 cells reduced their tumorigenic and metastatic properties, suggesting MUC4 may represent a gene that contributes to ALDH1A3/RA-mediated tumor growth and metastasis of MDA-MB-231 cells." (PMID 31590252, 2019). "However, when we stained for ALDH1A3, a known marker for breast CICs, we found serum erythropoietin levels negatively correlated with the number of putative breast CICs in the tumor sections." (PMID 30700319, 2019). "Similarly, patients expressing both c-Met and ALDH1A3 at tumor stage III-IV had poor prognosis (p = 0.0065)." (PMID 28966724, 2017). "Moreover, ALDH1A3 mRNA expression was also highly upregulated in the NB1 PDX tumor and in the SK-N-Be2c cell line during TIC selection, while it remained stable in the NB1-C cell line." (PMID 27724856, 2016). "Our data indicate that ALDH1A3+ HNSCC cells may contribute to tumor relapse after irradiation, and inhibition of this cell population might improve therapeutic response to radiotherapy." (PMID 26460734, 2015). "Finally, by mRNA knockdown we revealed the relationship between ALDH1A3 and the ability of tumor invasion." (PMID 26575197, 2015). "Moreover, we found that ALDH1A3 was most relevant to extracellular matrix organization and cell adhesion biological process, and the ability of tumor invasion was suppressed after ALDH1A3 knockdown in vitro." (PMID 26575197, 2015). "However, comparison of the xenografts that were treated 10 × 2 Gy fractions with untreated xenografts of the same HNSCC line revealed changes of ALDH1A3 fluorescence intensity that positively correlated with the TCD50 values of the five tumor models." (PMID 26460734, 2015). "Expression of the stem cell marker ALDH1A3 proceeded activation of hedgehog signaling and expression of inflammatory cytokines, increasing around day 15 post treatment and continued to be elevated during tumor regrowth." (PMID 28203638, 2015). "Secondly, an unresolved puzzle pertains to the precise role(s) of ALDH1A3 in tumor invasion." (PMID 26575197, 2015). "Therefore, our data suggest that initial ALDH1A3 expression cannot be used to predict the radioresistant potential of tumor cells." (PMID 26460734, 2015). "We also observed that the change of the ALDH1A3 expression level before and after radiotherapy may correlate with the tumor cell intrinsic radiosensitivity that could be attributed to an increase in other CSC markers." (PMID 26460734, 2015). "To inhibit ALDH1A3, we developed a hybrid in silico and high-throughput screening approach followed by medicinal optimization to identify first-in-class, oral and safe antagonists of ALDH1A3 with potent anti-tumor immunotherapeutic activity and an optimized drug development profile." (PMID 41210994, 2025). "Moreover, ALDH1A3 inhibitors may also modulate the immune response and enhance T-cell infiltration of tumors, resulting in the inhibition of tumor growth." (PMID 39001459, 2024). "Also, highly expressed ALDH1A3 played an important role in immune response of tumor." (PMID 36814901, 2023). "The significant associations in terms of metabolite changes in only the context of the in vivo tumor samples in comparison to the in vitro samples, suggested that the comparably nutrient poor tumor microenvironment is an important factor when assessing the impact of ALDH1A3 on the metabolome." (PMID 34989902, 2022). "Collectively, our findings urge to further delineate the protein modifiers involved in ALDH1A3 turnover, which may provide new insights for further testing the hypothesis that targeting ALDH1A3 may be effective in reducing the tumor-promoting potential of GSCs." (PMID 35052687, 2021).
tumor (continued). "Interestingly, PyMT tumor cells that were proximal to the C6:LP-NP cluster exhibited elevated Aldh1a3 expression, whereas there was an enrichment of cells with high Mfge8 expression towards the C7:LP-PI cluster, suggesting that the post-involution state is associated with increased Mfge8 expression." (PMID 32840210, 2020). "Therefore, co-expression of both c-Met and ALDH1A3 at late tumor stages may contribute to poor clinical outcome not only in Basal-like but also in other subtypes." (PMID 28966724, 2017). "Thus, chemotherapy treatment resulted in activation of the hedgehog pathway and release of inflammatory cytokines leading to long-term expansion of ALDH1A3 positive stem cells, which can contribute to the regrowth of the tumor and promote resistance to treatment." (PMID 28203638, 2015). "In addition, the potential utility of ALDH1A3 as a tumor biomarker was evaluated." (PMID 25969992, 2015). "For example, ALDH1A3 is a critical driver of breast CSC plasticity, metabolic reprogramming, and tumor progression." (PMID 40868269, 2025). "ALDH1A1 promotes tumor progression by enhancing the transcriptional activity of both the androgen receptor (AR) and the retinoic acid receptor (RAR), whereas ALDH1A3 appears to exert inhibitory effects." (PMID 40708788, 2025). "Considering our current data showing that tPA promotes metastasis of MDA‐MB‐231 cells and is inducible by ATRA, it also partly explains our prior findings where like ALDH1A3, ATRA increased metastasis of MDA‐MB‐231 tumours." (PMID 37753740, 2024). "We analyzed the harvested tumors at the termination of the experiment to evaluate the effect of ALDH1A3 knockdown and 2DG treatment on the percentage of CD24−CD44+ cells and the tumor-initiating cell frequency." (PMID 39251846, 2024). "In cell culture and tumor xenograft models, 2DG suppresses the increase in the CD24−CD44+ population and ROS induced by ALDH1A3 knockdown." (PMID 39251846, 2024). "We include representative images of patient tumour sections stained with ALDH1A3 and tPA, ALDH1A3 and uPA, and ALDH1A3 and PAI‐2 and include examples of patient tumour samples that had low and high ALDH1A3 staining." (PMID 37753740, 2024). "Microarray analysis of ALDEFLUOR+ and ALDEFLUOR– cells isolated from xenografted tumours indicated that the expression of ALDH1A1 and ALDH1A3 was more than 15 times higher in the ALDEFLUOR+ subpopulation." (PMID 36651035, 2023). "This study proves that ALDH1A3–Linc00284 upregulates TGFβ signaling through miR-361-5p, and then promotes the epithelial–mesenchymal transition (EMT) process and CRC tumor metastasis." (PMID 36275636, 2022). "Here, we investigated the role of the ALDH1A3–Linc00284 signal in CRC progression and in the tumor microenvironment through in-depth analysis of clinical data and in vitro experiments." (PMID 36275636, 2022). "The expression level of ALDH1A3 in CRC tissues (n = 73) was measured by qRT-PCR, in comparison with paired adjacent normal tissues, ALDH1A3 mRNA was significantly increased in tumor samples." (PMID 36275636, 2022). "By immunohistochemistry, a significant increase of ASCL4 and ALDH1A3 expression and a significant decrease of GPX4 expression was observed when comparing primary and corresponding recurrent tumor." (PMID 35530303, 2022). "The IHC staining results revealed that ALDH1A3 were upregulated induced DTX treatment and downregulated due to circCYP24A1 knockdown in tumor-bearing mice." (PMID 35831872, 2022). "In our studies, assessing the potential of ALDH1A3 and GABA on the TNBC, the most obvious effects was the impact of both ALDH1A3 and GABA in the increased metastasis to the lungs and brains of tumor-bearing animals." (PMID 34989902, 2022). "In tumor samples of CRC patients, miR-361-5p expression is negatively correlated with the expression of both ALDH1A3 and Linc00284." (PMID 36275636, 2022).
tumor (continued). "In tumors overexpressing ALDH1A3, the increase in tumor growth was sustained until the end of the experiments, while GABA treatment was insufficient to sustain the increased tumor growth." (PMID 34989902, 2022). "The results showed that the mRNA expressions of ALDH1A3, ALDH1L2, ALDH2, and ALDH3A2 were obviously related to tumor purity." (PMID 34928471, 2022). "NEDD9 overexpression significantly enhanced tumor sphere formation, and also elevated the expression of stemness-related transcription factors, including KLF4 and ALDH1A3." (PMID 33710809, 2021). "By co-culturing ESCC cells with G-MDSC, we observed enhanced NEDD9 expression, tumor sphere formation, and expression of stemness-related transcription factors, KLF4 and ALDH1A3." (PMID 33710809, 2021). "Wang and co-authors showed that the knockout of ALDH1A3 expression decreased in vitro invasive capacity of PC3 cells and in vivo xenograft tumor growth." (PMID 34572930, 2021). "In tumor immunity, the ALDH1 family (including ALDH1A1, ALDH1A2, and ALDH1A3) converts retinal to RA, which promotes the induction, function and stability of regulatory T cells, leading to immune tolerance that compromises tumor immunity." (PMID 32140062, 2020). "Among ALDH1A3 positive cells, there were some GFAP positive cells likely reactive astrocytes or tumor cells due to their distinct morphology." (PMID 32680476, 2020). "Double immunofluorescence staining revealed a co-localization of ALDH1A3 with GFAP in glial-shaped cells and in tumor cells." (PMID 32680476, 2020). "Importantly, ALDH1A3 blockade could significantly reduce tumor growth in vivo." (PMID 30538217, 2018). "We summarize that ALDH1A3 is a therapeutic target to diminish the ALDH activity and represents the stemness of tumor cells in vitro." (PMID 30538217, 2018). "ALDH1A3 was considered to be the isoenzyme responsible for ALDH activity and tumorigenicity in tumor cells." (PMID 28253891, 2017). "In this study, we first confirmed the enrichment of ALDH1A2 and ALDH1A3 expression during NB TICs selection in one PDX tumor (NB1), as well as in two distinct cell lines, the NB1-C cells derived from the NB1 PDX tumor, and/or the I-type SK-N-Be2c cell line." (PMID 27724856, 2016). "We tested possible expression changes of five genes (TACSTD, MMP7, ALDH1A3, MKI67, GLUT1) in tumors 48 h and 14 days after mTHPC and Lipidot mediated PDT compared to untreated tumor controls." (PMID 27716314, 2016). "We found that ALDH activity, which is, at least partially, attributed to ALDH1A3 isoform, is indicative of those HNSCC tumor progenitors." (PMID 26460734, 2015). "Additionally, cells with knocked down ALDH1A3 or the other key genes FAM3C, PMEPA1, and MCC showed reduced tumor xenograft growth and metastasis in mice, highlighting their role in tumor progression." (PMID 40781158, 2025). "In addition, we performed tumor immune dysfunction and exclusion (TIDE) prediction, which showed that the TIDE score was higher in the group with low expression of ALDH1A3, suggesting that these patients responded less well to immunotherapy." (PMID 40227735, 2025). "Unresolved conceptual ambiguity around the role of ALDH1A3 in the regulation of GSC stemness reflects the general lack of consensus regarding the role of self-renewal in the tumor-propagating capacity of GSCs." (PMID 39513909, 2024). "We, therefore, confirmed the ALDH1A3‐dependent regulation of PLAT, PLAU, and SERPINB2 by RT‐qPCR and visualized the co‐expression correlation of the genes with ALDH1A3 in the patient tumour data." (PMID 37753740, 2024). "In agreement with our previous work, ALDH1A3 knockdown in MDA-MB-468 cells increases tumor growth (as per tumor volumes and final tumor weights), and as hypothesized, treatment of the mice with 2DG in their water blocks this effect (left)." (PMID 39251846, 2024). "In contrast, ALDH1A3 is more frequently highly expressed in primary tumor samples but not in distant metastasis." (PMID 38169509, 2024).
tumor (continued). "Although these co‐expression analyses in patient tumour data suggest a potential connection between ALDH1A3 and these proteases and protease regulators, it does not necessarily mean direct regulation of the genes by ALDH1A3." (PMID 37753740, 2024). "Therefore, to investigate potential mechanisms for ALDH1A3‐mediated invasion, we assessed the TCGA RNAseq and METABRIC gene array data for gene co‐expression with ALDH1A3 in TNBC tumours." (PMID 37753740, 2024). "Additionally, based on our previous results, we found ALDH1A3 to be highly expressed in relapsed GBM, further supporting its role in tumor recurrence." (PMID 37947601, 2023). "NR6 treatment prevented neutrophil recruitment by exerting its effect on tumour cells, as neutrophils did not express ALDH1A3 and were insensitive to its inhibition." (PMID 37047661, 2023). "The results also revealed that ALDH1A2 expression is highest in mesothelioma (data not shown) and that the tumour type with the highest ALDH1A3 expression level is prostate cancer." (PMID 36651035, 2023). "Among them, ALDH1A3, one of the ALDH1 subtypes, is located on chromosome 15q26.3 and is abnormally expressed in various tumor tissues, participating in regulating the biological function of tumor cells." (PMID 36980923, 2023). "Indeed, Aldh1a3 expression and ALDH enzyme activity were elevated in AT-ECs of tumor-bearing mice compared to in tumor-free wild-type mice." (PMID 37749321, 2023). "Double immunofluorescence staining demonstrated a co-localization of the immunoreactivity of ALDH1A3 (red) with PAI-1 (green) or with IL-8 (green) in vessels (arrows), the peripheral cells of glomeruloid bodies (arrowheads), and in tumor cells (asterisks)." (PMID 37686698, 2023). "Our comparison of two DCIS regions in Sample #1 reveals reduced myoepithelial markers KRT15, KRT23, and ALDH1A3 and increased invasive markers in DCIS #2 which could indicate a higher grade tumor." (PMID 38114474, 2023). "ALDH1A3 activates the PI3K/AKT/mTOR signalling pathway and its downstream target PPARγ, leading to increased expression of HK2, which in turn increases glycolysis in pancreatic ductal carcinoma cells, thereby promoting tumour metastasis." (PMID 36651035, 2023). "High expression of ALDH1A3 in MES-GSCs induced mesenchymal differentiation, rapid intracranial tumor growth, and invasiveness, thereby leading to an aggressive progression of the tumor." (PMID 37686698, 2023). "This suggests that ALDH1A3 has effects in the tumor microenvironment that are not fully explained by ALDH1A3’s effects on GABA metabolism and signaling." (PMID 34989902, 2022). "Likely the ALDH1A3 overexpression provides an additional advantage not imparted by GABA treatment that better supports the increased growth of the tumor cells." (PMID 34989902, 2022). "ALDH1A3 and STAT1 mRNA levels were significantly upregulated in tumor samples." (PMID 34440089, 2021). "Overall, our results show that the expression of NANOG and ALDH1A3 remains stable during metastasis, probably not affected by change in the tumor microenvironment." (PMID 32423137, 2020). "Finally, NRAD1 is a novel downstream target of aldehyde dehydrogenase 1A3 (ALDH1A3) and the first lncRNA described to contribute to gene expression changes induced by this CSC marker and mediator of tumor progression." (PMID 31197235, 2020). "As the co-expression of ALDH1A3 with the stem cell marker CD44 was also found, we propose that ALDH1A3 positive tumor cells might possess the stem cell-like properties involved in tumor progression and therapy resistance." (PMID 32680476, 2020). "ALDH1A3 staining was cytoplasmic and showed a diffuse pattern throughout the tumors where complete tumor islands were often positive with little evidence of any preferential peripheral staining within those islands." (PMID 26880935, 2016).